FKBP9 (FKBP prolyl isomerase 9)
Description:
PPIases accelerate the folding of proteins during protein synthesis.
Synonyms: FKBP60; FKBP63; PPIase
Tractability: Small molecule: it belongs to a druggable protein family. Antibody: UniProt predicts a signal peptide or a membrane-spanning region. PROTAC: ubiquitination databases record sites on it; its protein half-life has been measured.
Gene: Protein-coding gene on chromosome 7 (32,957,404 to 33,006,930, forward strand). Ensembl gene ENSG00000122642.
Subcellular location: Endoplasmic reticulum
Subcellular location (Human Protein Atlas): Golgi apparatus
Pathways (Reactome):
Metabolism of proteins: Association of TriC/CCT with target proteins during biosynthesis
Gene Ontology:
Molecular function: calcium ion binding; peptidyl-prolyl cis-trans isomerase activity
Biological process: protein folding
Cellular component: endoplasmic reticulum
Genetic constraint (gnomAD): Loss-of-function variants: 27 observed, 51.08 expected, observed/expected ratio (o/e) 0.53, 90% interval 0.39 to 0.73. The upper end of that interval is the gene's LOEUF score, 0.73, which puts it in group 2 of 6, group 1 being the genes least tolerant of losing a copy. Missense variants: 533 observed, 689.22 expected, observed/expected ratio (o/e) 0.77, 90% interval 0.72 to 0.83. Synonymous variants: 264 observed, 275.36 expected, observed/expected ratio (o/e) 0.96, 90% interval 0.87 to 1.06.
Homologues: Orthologues: chimpanzee FKBP9 (99% identical), rabbit FKBP9 (98% identical), dog FKBP9 (97% identical), pig FKBP9 (97% identical), rat Fkbp9 (94% identical), mouse Fkbp9 (94% identical), macaque FKBP9 (90% identical), guinea pig FKBP9 (84% identical), tropical clawed frog fkbp9 (76% identical), zebrafish fkbp9 (66% identical), Caenorhabditis elegans fkb-5 (15% identical), Caenorhabditis elegans fkb-4 (12% identical). Paralogues in human: FKBP10 (56% identical), FKBP15 (15% identical), FKBP5 (15% identical), FKBP4 (13% identical), FKBP3 (12% identical), FKBP7 (11% identical), FKBP14 (11% identical), FKBP2 (10% identical), FKBP8 (9% identical), FKBP11 (9% identical), FKBP1A (9% identical), FKBP1C (8% identical), and 6 more.
Diseases named in the same sentence as FKBP9 in open-access papers:
FKBP9 is named in the same sentence as 13 diseases in open-access papers, as found by Europe PMC text mining. Sharing a sentence is not in itself a finding about the gene and the disease. The quoted sentences say what the papers report.
glioma (6 papers, 2019 to 2025). A benign or malignant brain and spinal cord tumor that arises from glial cells (astrocytes, oligodendrocytes, ependymal cells). "Taken together, our data indicated the carcinogenesis of FKBP9 in glioma, and revealed that knockdown of FKBP9 causes ER stress." (PMID 32111229, 2020). "Moreover, a mutation of methionine (M) 541 into isoleucine (I) in FKBP9 was found in clinical glioma tissue samples." (PMID 32111229, 2020). "Of interest, an M541I variant of FKBP9 was found in clinical glioma tissue samples." (PMID 32111229, 2020). "BiP and FKBP9 protein levels were positively correlated in patients with glioma, and patients with high expression of BiP and FKBP9 showed a worse prognosis." (PMID 39281835, 2024). "Overexpression of the genes whose transcripts act as potential targets fordysregulated miRNAs in the IDHmut and IDHwt groups is observed in moreaggressive glioma types: FKBP9 – CREB3L4, MCM4, MCM6, PSMB2, ARID1A, ARL4C, GRPEL2, and C9orf64." (PMID 39539523, 2024). "In this study, we try to identify factors that regulate FKBP9 expression in glioma and illustrate the impact of FKBP9 ablation on the overall survival of genetically engineered FKBP9 conditional knockout mice with orthotopic glioma." (PMID 39281835, 2024). "Immunohistochemical analysis in a tissue microarray containing 17 adjacent normal brain tissues and glioma tissues showed that both BiP and FKBP9 expression were markedly elevated in tumor tissues compared with paired adjacent normal brain tissues." (PMID 39281835, 2024). "The results showed that BiP or FKBP9 expression in patients with glioma was significantly higher than that in normal tissues." (PMID 39281835, 2024). "Given that BiP directly binds with FKBP9 in glioma cells, to determine the possible role of BiP in regulating FKBP9, we characterized the molecular consequences of BiP knockdown in glioma cells." (PMID 39281835, 2024). "Of interest, FKBP9 is highly amplified in gliomas across most cancer types, as revealed by an initial survey of the TCGA database." (PMID 32111229, 2020). "A previous study by Verhaak and colleagues reported a mutation of methionine (M) at position 541 into isoleucine (I) in FKBP9 in clinical glioma tissue samples." (PMID 32111229, 2020). "The correlation between FKBP9 expression levels and the clinical prognosis of glioma patients was examined by bioinformatic analysis." (PMID 32111229, 2020). "The results showed that high FKBP9 expression correlated with reduced overall survival (OS) of glioma patients." (PMID 32111229, 2020). "Our results show that BiP promotes FKBP9 protein stabilization and patients with both high expression of BiP and FKBP9 show a worse prognosis, indicating that the BiP–FKBP9 axis may play an important role in glioma patients." (PMID 39281835, 2024). "However, BiP is abundantly and excessively expressed in cells, exceeding FKBP9 expression by more than 100-fold in glioma cells." (PMID 39281835, 2024). "FKBP9 up-regulation predicts poor survival of patients with glioma." (PMID 39281835, 2024). "Furthermore, co-immunoprecipitation also confirmed the interaction between endogenous FKBP9 and endogenous BiP in T98G and U251 glioma cells." (PMID 39281835, 2024). "Importantly, the immunohistochemical expression analysis for FKBP9 plotted against BiP indicated a significant positive correlation between BiP and FKBP9 expression in patients with glioma." (PMID 39281835, 2024). "High FKBP9 expression correlated with poor prognosis in glioma patients." (PMID 32111229, 2020). "The expression of FKBP9 in clinical glioma tissues was detected by immunohistochemistry (IHC)." (PMID 32111229, 2020). "FK506-binding protein 9 (FKBP9) is amplified in high-grade gliomas (HGGs)." (PMID 32111229, 2020). "Our results also showed that FKBP9 could be degraded by ubiquitination with Tg treatment, which would implicate a novel therapeutic avenue for the treatment of glioma." (PMID 32111229, 2020).
glioma (continued). "Our initial survey of the cBio Cancer Genomics Portal revealed that FKBP9 is amplified in gliomas, suggesting that FKBP9 might play a role in GBM biology." (PMID 32111229, 2020). "Bioinformatics analyses of available different public datasets all indicated that FKBP9 is upregulated in human high-grade gliomas and that high FKBP9 expression correlates with reduced overall survival of GBM patients, further supporting a role for FKBP9 in GBM." (PMID 32111229, 2020). "Notably, higher FKBP9 expression was also observed in GBM compared with low-grade glioma (LGG, WHO grade I and II gliomas)." (PMID 32111229, 2020). "However, the upstream regulatory mechanism of FKBP9 expression in glioma remains unknown and is worth exploring." (PMID 39281835, 2024). "The IHC findings confirmed the increased expression of AEBP1, DCTD, DEPP1, DUSP6, FKBP9, and UGCG with the up‐regulation of glioma grades." (PMID 40052358, 2025). "Further, the Chinese Glioma Genome Atlas (CGGA) database was utilized for Kaplan–Meier survival analysis, taking into account the expression levels of BiP and FKBP9." (PMID 39281835, 2024). "However, the precise role and mechanism(s) of action of FKBP9 in glioma remain completely unknown." (PMID 32111229, 2020). "However, the roles and mechanism(s) of FKBP9 in glioma are unknown." (PMID 32111229, 2020). "FKBP9 has been reported to play important roles in glioma, but the factors that regulate FKBP9 expression have never been investigated." (PMID 39281835, 2024). "Though CLEC5A and FKBP9 have not been reported in glioma-related studies, their features play important roles in cell metabolism and pathological processes." (PMID 31508371, 2019). "Therefore, CLEC5A, FMOD, FKBP9, and LGALS8 could be considered crucial prognostic factors in the OS of glioma patients." (PMID 31508371, 2019).
glioblastoma (5 papers, 2020 to 2024). The most malignant astrocytic tumor (WHO grade IV). "FKBP9 is an ER-resident protein that serves as a molecular chaperone in glioblastoma, aiding protein folding and mitigating protein misfolding in the ER lumen." (PMID 39281835, 2024). "We further identified that FKBP9 has relatively high levels in tumor cell lines including glioblastoma, breast cancer, lung cancer, and liver cancer, compared with non-transformed human cell line HEK-293T." (PMID 39281835, 2024). "To further explore the effects of FKBP9 expression on glioblastoma progression in vivo, we performed orthotopic mouse xenograft experiments." (PMID 32111229, 2020). "FKBP9 is a poor prognostic biomarker for isocitrate dehydrogenase 1/2 (IDH) wild-type glioblastoma." (PMID 39281835, 2024). "Another study further confirmed that FKBP9 up-regulation could confer glioblastoma cell resistance to endoplasmic reticulum (ER) stress through ASK1-p38 signaling." (PMID 39281835, 2024). "One previous study showed that FKBP9 could confer glioblastoma cell resistance to ER stress through ASK1-p38 signaling." (PMID 39281835, 2024). "Thus, FKBP9, the most controlled gene in nodule “P”, is known for promoting malignant behavior of glioblastoma cells and poor prognosis of PCa patients." (PMID 35723406, 2022). "Another study found that FKBP9 is a critical factor for promoting the malignant behaviors of glioblastoma cells; high FKBP9 level is related to poor prognosis and could confer malignant cells with the capability to resist endoplasmic reticulum stress inducers." (PMID 34917619, 2021). "Glioblastoma (GBM) cell lines stably depleted of FKBP9 were established using lentiviruses expressing shRNAs against FKBP9." (PMID 32111229, 2020).
breast carcinoma (3 papers, 2020 to 2024). "Other studies have also confirmed that FKBP9 is connected with other cancers, such as colorectal and breast cancers." (PMID 34917619, 2021). "A related protein, FKBP9, also was up-regulated in stage 2 breast cancer tissue." (PMID 31945087, 2020).
leukaemias (2 papers, 2010 to 2021). "Fkbp9 (FK506 binding protein 9) is strongly expressed in the megakaryoblastic leukaemias with a weaker but sustained expression in other types of leukaemias." (PMID 20102610, 2010). "Moreover, numerous genes are being reported for the first time and some of these genes are candidate oncogenes: Fgf3, Nmyc, Fap, Myct1, Gucy1a3, Gulp1 and Fkbp9 specific to megakaryoblastic leukaemias and Ssx2ip, Rab11a, Ncoa3, Snca, Ltbp2, Rabgef1 and Btbd14a specific to erythroleukaemias." (PMID 20102610, 2010). "Among the other genes with strong correlations between DNA methylation and gene expression, aberrant DNA methylation and downregulation of FKBP9, CA8, MSC, TRPC6, ZNF492, ZNF229, and ZNF471 genes in leukemia patients are reported here for the first time." (PMID 34575904, 2021).
lung carcinoma (2 papers, 2022 to 2024). "FKBP10, the protein most structurally similar to FKBP9, has been reported to interact with ribosomes to regulate protein translation in sustaining lung cancer growth." (PMID 39281835, 2024).
oropharyngeal cancers (1 paper, 2019). Carcinoma, predominantly squamous cell, arising from the epithelial cells of the oropharynx. "A similar differential analysis in the HPV- cohort indicated a panel completely distinct from the HPV+ oropharyngeal cancers; FADD (Fas Associated via Death Domain, 41%), FKBP9 (FKBP Prolyl Isomerase 9, 24%), FLNA (Filamin A, 24%) and DNMT3B (DNA Methyl transferase 3 Beta, 18%) with high prevalence." (PMID 31310629, 2019).
tumor (7 papers, 2015 to 2025). "We further expanded that the knockdown of FKBP9 inhibited the proliferation of various tumor cell lines." (PMID 39281835, 2024). "FK506-binding protein 9 (FKBP9) is involved in tumor malignancy by resistance to endoplasmic reticulum (ER) stress, and the up-regulation of FKBP9 is associated with patients' poor prognosis." (PMID 39281835, 2024). "Depletion of FKBP9 in SF-539 cells led to a substantial decrease in both tumor growth and vascular invasion in the CAM model compared to the control." (PMID 32111229, 2020). "The most abundant protein observed in early‐stage tumor tissues was FKBP9 (peptidyl‐prolyl cis‐trans isomerase FKBP9) (upregulated in early‐stage tumor tissues)." (PMID 32536039, 2020). "Expression of the FK506 binding proteins FKBP4, FKBP6, and FKBP9, immunophilins known to interact with mTOR, was upregulated in DC-tumor fusions 5.3-, 6.7-, and 28-fold." (PMID 26605345, 2015). "In addition to carrying the Braf gene, chromosome 6 carries several genes that are highly expressed in the LNM and tumor populations (Aqp1, Col1a2, Cav1, Cav2, Ptn, RaRes2, Fkbp9, Actg2, Ybx3, Mgp, Sox5, Kcna1, and Ptms)." (PMID 40571713, 2025). "Additionally, DUSP6 has shown significant up‐regulation and tumor‐promoting properties in GBM, while FKBP9 has been implicated in fostering the malignant behavior of GBM cells and conferring resistance to endoplasmic reticulum stress inducers." (PMID 40052358, 2025). "Knockdown of FKBP9 markedly suppressed the malignant phenotype of GBM cells in vitro and inhibited tumor growth in vivo." (PMID 32111229, 2020).
cancer (6 papers, 2020 to 2024). A tumor composed of atypical neoplastic, often pleomorphic cells that invade other tissues. "It has been reported that FKBP9 is associated with metastasis and poor prognosis in a variety of cancers." (PMID 36263422, 2022). "Notably, FKBP9 is associated with cancers, including distant metastasis and the promotion of cancer progression." (PMID 39281835, 2024). "Although the proposed therapeutic overexpression will restore the normal expression of FKBP9 in all three cancer nodules, while upregulating it in “Z”, it would have significant consequences only on “P”, owing to the low FKBP9 GCH scores in the other three regions." (PMID 35723406, 2022). "Thus, by therapeutically increasing the expression of FKBP9 (downregulated in all three cancer nodules with respect to “Z”), the expressions of its synergistic partner genes would be pushed up, while the antagonistically expressed ones would be pushed down." (PMID 35723406, 2022). "Among the ER-resident FKBPs, the role of FKBP9 in cancer remains largely unknown." (PMID 32111229, 2020). "For instance, FKBP9, the GMR of “P”, was similarly downregulated in all three cancer nodules: x = −1.52 (WIR = −7.44) in “P”, x = −1.59 (WIR = −8.51) in “Q” and x = −1.49 (WIR = −6.97) in “M”." (PMID 35723406, 2022). "Thus, FKBP9 may be an effective feature of many cancer cell lines." (PMID 34917619, 2021). "On the other hand, a new set of potential biomarkers (NCKAP1, TNFRSF12A, LAMB2, FKBP9, PFN2, TOM1L1) and expression rules for the identification of different cancers at the transcriptome level were discovered." (PMID 34917619, 2021).
FKBP9 also shares sentences with these, for which no sentence is quoted: atherosclerosis (1 paper); diabetes (1); glaucoma (1); liver cancer (1); prostate carcinoma (1).